JAK1 (Janus kinase 1)
Diseases named in the same sentence as JAK1 in open-access papers (continued):
Sharing a sentence is not in itself a finding about the gene and the disease.
Obesity (4 papers, 2019 to 2023). Accumulation of substantial excess body fat. "First, we identified gene sets related to the function of each obesity-related serum factor: HG/HI (Insr, Irs1, Rps6kb1, Slc2a4, Slc2a5, Slc2a1), TNF-α (Tnfrsf1a, Tradd, Traf2, Fadd), IL-6 (Il6ra, Il6st, Jak1), and fatty acids (PA, LA, Chol; Ffar1, Ffar4, Ppara, Pdk4, Pgc1a)." (PMID 37047207, 2023).
peripheral T-cell lymphoma (4 papers, 2021 to 2026). "Golidocitinib represents a groundbreaking Class 1 novel drug independently developed in China, marking the first highly selective small molecule inhibitor of JAK1 inhibitor globally approved for relapsed or refractory peripheral T-cell lymphoma." (PMID 40895526, 2025).
rheumatic diseases (4 papers, 2024 to 2025). "Tofacitinib is an Janus kinase 1/3 inhibitor that demonstrated its efficacy in many rheumatic diseases." (PMID 38360816, 2024). "The three drugs that are routinely used and discussed in rheumatic diseases are tofacitinib (TOFA; works on JAK families in this order- JAK3 > JAK2 > JAK1), baricitinib (BARI; JAK1, JAK2, and TYK2), and upadacitinib (UPA; JAK1 > JAK2 and JAK3)." (PMID 40282506, 2025). "JAKi, with varying selectivity for JAK1, JAK2, JAK3, and Tyk2, have then the role of disrupting proinflammatory cytokine cascades in rheumatic diseases." (PMID 38554250, 2024).
Stroke (4 papers, 2022 to 2026). Sudden impairment of blood flow to a part of the brain due to occlusion or rupture of an artery to the brain. "Among the JAK/STAT family members, activation of the JAK1/STAT3 pathway has shown anti-inflammatory effects in stroke." (PMID 40649310, 2025). "We revealed that kaempferol regulates post-stroke apoptosis and neuroinflammation involved by neutrophils, and the underlying mechanism may be related to the regulation of BDNF-TrkB-PI3K/AKT signaling and JAK1/STAT3 signaling, respectively." (PMID 36293548, 2022). "The activation of specific Janus kinase-signal transducers and activators of transcription (JAK/STAT) signaling pathway such as JAK1/STAT3, by propofol has been reported to be neuroprotective in stroke." (PMID 40649310, 2025).
thyroid cancer (4 papers, 2012 to 2024). "The expression level of JAK1 was higher in clear cell renal cell carcinoma, papillary renal cell carcinoma, and thyroid carcinoma." (PMID 33323549, 2020). "In this study, we determined the sensitivity of thyroid cancer cell lines harboring oncogenic forms of RET to JAK1/2 inhibitor, AZD1480." (PMID 23056499, 2012). "Thus, the more malignant the thyroid cancer, the higher JAK1/2-STAT3 pathway activation." (PMID 38336839, 2024). "Recently, the efficacy of the JAK1/2 inhibitor AZD1480 against the growth of thyroid cancer was tested in vitro and in vivo in thyroid cancer cell lines that expressed oncogenic RET." (PMID 23509459, 2013). "Herein, we investigated the biological effects of a JAK1/2 inhibitor, AZD1480, on the growth of PTC- and MTC- derived thyroid cancer cell lines harboring activating RET/PTC rearrangements and RET mutations, respectively." (PMID 23056499, 2012). "Here, we tested the efficacy of a JAK1/2- inhibitor, AZD1480, in the in vitro and in vivo growth of thyroid cancer cell lines expressing oncogenic RET." (PMID 23056499, 2012). "In conclusion, we showed that the JAK1/2 inhibitor, AZD1480, can block the growth and induce cell death of thyroid cancer cell lines harboring distinct forms of oncogenic RET in vitro and in vivo." (PMID 23056499, 2012). "Furthermore, through examination of the expression of JAK1, p-JAK1, JAK2, p-JAK2, STAT3, and p-STAT3 in diverse thyroid cancer cell lines, it was discovered that ATC cells exhibit elevated levels of background expression." (PMID 38336839, 2024).
tuberculosis (4 papers, 2022 to 2025). A chronic, recurrent infection caused by the bacterium Mycobacterium tuberculosis. "Baricitinib, a selective JAK1 and JAK2 inhibitor, may predispose to tuberculosis by suppressing interferon-gamma (IFN-γ)-mediated signaling, which is essential for macrophage activation and granuloma maintenance." (PMID 40735451, 2025). "Dear Editor, We report on a 68-year-old Caucasian male with a 6-year history of PsA who developed pulmonary and lymph node tuberculosis (TB) 6 months after initiation of treatment with the Janus kinase 1 (JAK1) inhibitor upadacitinib." (PMID 35601270, 2022).
acute leukemia (3 papers, 2010 to 2023). A clonal (malignant) hematopoietic disorder with an acute onset, affecting the bone marrow and the peripheral blood. "Recently the JAK1 V658F mutation was also identified from a screen of acute leukemia patients." (PMID 20585391, 2010). "JAK1 and JAK3 mutations were also found in human acute leukemias and solid cancers." (PMID 23704931, 2013).
bone marrow fibrosis (3 papers, 2013 to 2025). "Ruxolitinib is a potent JAK1/JAK2 inhibitor, approved for the treatment of primary myelofibrosis (PMF) patients based on the concept of inhibition of oncogenic signaling." (PMID 40413183, 2025).
breast invasive carcinoma (3 papers, 2017 to 2026). "For example, JAK1 expression is significantly reduced in breast invasive carcinoma and assocites with prognosis and immune infiltration." (PMID 41511940, 2026). "JAK1 expression was significantly lower in breast invasive carcinoma (BRCA) compared with adjacent normal tissues." (PMID 31790361, 2019). "JAK1 expression was significantly lower in breast invasive carcinoma compared with adjacent normal tissues." (PMID 31790361, 2019). "JAK1 mRNA expression was significantly lower in breast invasive carcinoma compared with adjacent normal tissues." (PMID 31790361, 2019).
breast tumor (3 papers, 2019 to 2024). "Therefore, we tested whether breast tumor JAK1 mRNA levels correlated with the T cell transcript-enriched LYM metagene signature." (PMID 31790361, 2019). "As a proof of concept, B2m, Jak1, and Psmb9 single gene KOs were generated using the murine EMT6 breast tumor model to promote PD-1 or PD-L1 ICB resistance." (PMID 38427670, 2024). "Whether the JAK1 mRNA levels in breast tumors correlates with outcome has not been evaluated." (PMID 31790361, 2019).
coccidioidomycosis (3 papers, 2024 to 2025). A fungal infection caused by Coccidioides immitis. "RUX, a Janus-associated kinase 1/2 (JAK1/2) inhibitor used in PV treatment, has been associated with various infections, but its link to coccidioidomycosis remains underexplored." (PMID 40322414, 2025). "This case report explores the consequences of inhibiting JAK1 and JAK2 via ruxolitinib, particularly in the context of fungal defense in a patient diagnosed with pulmonary coccidioidomycosis." (PMID 41164159, 2025). "In a recent case series of 135 patients receiving ruxolitinib (JAK1/JAK2 inhibitor), 8 developed symptomatic coccidioidomycosis; 4 had coccidioidomycosis preceding ruxolitinib, and each had primary pulmonary disease while on therapy." (PMID 38667927, 2024).
colorectal tumor (3 papers, 2017 to 2025). "Preclinical data suggest that inhibition of JAK1 can block colorectal tumor growth, supporting a potential positive prognostic value of inactivating mutations, but additional analyses are required to explain the role of JAK1 mutations in the progression of MSI+ CRC." (PMID 28539123, 2017). "Studies have shown that lactate derived from colorectal tumors directly mediates the lactylation of the methyltransferase‐like METTL3 zinc finger domain, which enhances the binding and catalytic activity of METTL3 on Janus kinase 1 (JAK1) mRNA, facilitating m6A modification." (PMID 40443721, 2025).
fibrosis (3 papers, 2021 to 2024). the formation of excess fibrous connective tissue in an organ or tissue in a reparative or reactive process. "In a bleomycin‐induced fibrosis mouse model, JAK1 is overexpressed in lung tissues and is predominantly localized within inflammatory and epithelial cells." (PMID 39253319, 2024). "JAK1/2 regulates the function of HSCs and plays an essential role in liver fibrosis and HCC development." (PMID 35382859, 2022). "In AECs from both a BLM-induced fibrosis mouse model and pulmonary fibrosis patients, IL-4 and IL-13 mediate their fibrotic effect by binding to the receptor and activating JAK1." (PMID 34207510, 2021). "Also, Ruxolitinib, the JAK1/2 selective inhibitor, blocked HSCs activation, both in cell culture and in animal fibrosis models, included by CCl4 and Thioacetamide (TAA)." (PMID 35382859, 2022). "JAK1 is overexpressed in lung tissue and localized in inflammatory and epithelial cells of bleomycin (BLM)-induced fibrosis mouse model." (PMID 34207510, 2021).
gastric adenocarcinoma (3 papers, 2017 to 2025). "Research has also found that lycopene inhibits the proliferation of Helicobacter pylori-infected gastric adenocarcinoma cells by reducing ROS levels and inhibiting Jak1/Stat3 activation, Wnt/β-catenin signaling, and oncogene expression." (PMID 38287248, 2024). "Analyzing gene expression signatures in endometrial and stomach adenocarcinomas revealed that tumors with a JAK1 frameshift exhibited reduced expression of interferon response signatures and multiple anti-tumor immune signatures." (PMID 29121062, 2017). "Stomach adenocarcinomas with a JAK1 frameshift exhibited reductions in both interferon responses but reductions in IL-6 and IL-2 responses were not significant." (PMID 29121062, 2017). "In stomach adenocarcinoma (STAD), 1/293 (0.3%) MSS samples, 2/63 (3.2%) MSI-L samples, and 20/85 (23.5%) MSI-H samples had a frameshift in JAK1, which was also statistically significant when comparing MSS and MSI-H groups (P < 0.0001, Fisher’s exact test)." (PMID 29121062, 2017).
HCMV infection (3 papers, 2014 to 2023). "We confirmed known effects of HCMV infection on Jak1, STAT2, and IRF9 and demonstrated that, apart from STAT1, expression of the final effectors in both interferon induction and response pathways were all progressively diminished during infection." (PMID 24906157, 2014). "HCMV infection is reported to induce the proteasomal degradation of janus kinase 1 (JAK1) by unknown mechanisms." (PMID 37289831, 2023). "Total JAK1 levels decreased throughout HCMV infection but were not differentially regulated in WT and ΔUL138STOP infections." (PMID 37289831, 2023).
heart failure (3 papers, 2025 to 2026). Inability of the heart to pump blood at an adequate rate to meet tissue metabolic requirements. "In the validation set GSE5406, the expression of JAK1 was dramatically downregulated, while EIF2AK2 was significantly upregulated in heart failure (HF) tissues." (PMID 39704101, 2025).
Herpes simplex infection (3 papers, 2022 to 2025). "Ruxolitinib is a JAK1/2 inhibitor that promotes vesicular stomatitis, herpes simplex, and measles viral replication in cell culture." (PMID 37760788, 2023).
hypereosinophilic syndrome (3 papers, 2021 to 2025). Hypereosinophilic syndrome (HES) constitutes a rare and heterogeneous group of disorders, defined as persistent and marked blood eosinophilia and/or tissue eosinophilia associated with a wide range of clinical manifestations reflecting eosinophil-induced tissue/organ damage. "STAT5B acts downstream of JAK1, a gene in which gain-of-function mutations reportedly cause hypereosinophilic syndrome, and it is the target of the approved AD therapeutic agent baricitinib." (PMID 41357518, 2025).
Hyperglycemia (3 papers, 2024 to 2025). An increased concentration of glucose in the blood. "The JAK1/JAK2 inhibitor LN3103801 prevents/reverses hyperglycemia by dual blockade of IFN-γ-mediated MHC-I overexpression in beta-cells and γc cytokine-driven T-cell activation, without compromising antitumor efficacy in NOD mice." (PMID 40534861, 2025). "The observed metabolic acidosis and hyperglycemia are interpreted as manifestations of severe systemic stress and acute toxicity rather than as direct effects of JAK1 inhibition." (PMID 41562806, 2025).
ischemia (3 papers, 2017 to 2026). A hypoperfusion of the BLOOD through an organ or tissue caused by a PATHOLOGIC CONSTRICTION or obstruction of its BLOOD VESSELS, or an absence of BLOOD CIRCULATION. "In vivo, rats subjected to transient middle cerebral artery occlusion (tMCAO) received intravenous ADSC-CM or vehicle at 2, 24, and 48 h post-ischemia, with or without the JAK1 inhibitor GLPG0634." (PMID 41809974, 2026). "A previous study showed that JAK1 and STAT3 are activated in neurons, astrocytes and microglia after focal cerebral infarction, and may provide neuroprotection in the acute phase of ischemia." (PMID 28542400, 2017). "Previous studies have shown that after focal cerebral infarction, the activation of JAK1 and STAT3 in microglia may provide neuroprotection in the acute phase of ischemia." (PMID 28542400, 2017).
keratinization disease (3 papers, 2021 to 2025). "Since then, endotypes underlying novel entities matching the concept of autoinflammatory keratinization diseases have been discovered (mutations of JAK1, POMP, and EGFR)." (PMID 38103162, 2023). "This study identifies another previously unreported heterozygous missense JAK1 mutation, H596D, in an individual with a unique autoinflammatory keratinization disease associated with early-onset liver dysfunction and autism." (PMID 35046931, 2021). "In this study, we identify a further previously unreported heterozygous missense mutation in JAK1 in an individual with inflammatory skin changes of a unique autoinflammatory keratinization disease (AiKD) associated with early-onset liver dysfunction and autism." (PMID 35046931, 2021). "Future research should prioritize controlled clinical trials to confirm its efficacy and safety, as well as translational studies to uncover the interactions between the JAK1 signaling pathway and the pathogenesis of keratinizing disorders, especially in patients with EPPP/PK." (PMID 40959436, 2025). "This dual effect suggests that selective JAK1 inhibition may offer therapeutic potential in inflammatory keratinization disorders such as EPPP." (PMID 40959436, 2025).
Large Granular Lymphocyte Leukemia (3 papers, 2014 to 2020). "Therefore, we report and characterize a novel gain-of-function Jak1 mutation in a spontaneous LGL leukemia model that results in increased downstream STAT signaling." (PMID 31947841, 2020). "While JAK1 mutations have not been reported in LGL leukemia patients, mutations in JAK1 have been identified in several hematological malignancies." (PMID 31947841, 2020). "A recent clinical investigation has shown the JAK1/JAK3 inhibitor tofacitinib to be a promising salvage therapy for refractory T-LGL leukemia patients with or without STAT3 mutations." (PMID 29228628, 2017). "IL2 and IL15 activate lymphoproliferative signaling through JAK1/JAK3-STAT3/STAT5 and IL15 has shown to be elevated in large granular lymphocytic leukemia." (PMID 29228628, 2017). "Furthermore, CK2 inhibition diminished the Jak1- and Src kinase-dependent phosphorylation of a constitutively active STAT3 mutant recently described in human large granular lymphocytic leukemia." (PMID 24742922, 2014).
lichen planus (3 papers, 2016 to 2025). A chronic, recurrent, pruritic inflammatory disorder of unknown etiology that affects the skin and mucus membranes. "Studies show JAK1 and JAK3 overexpression in lichen planus (LP) inflammatory infiltrates, implicating JAK signaling in its pathogenesis." (PMID 41523413, 2025).
liver disease (3 papers, 2022 to 2023). "Previous reports revealed that JAK1 expression is highly elevated in children with liver disease and that JAK1-signaling pathway is significantly activated in children with ASD, suggesting the association of neuroinflammation." (PMID 38026692, 2023). "In the present study, we found up-regulated JAK1 and JAK2 were associated with liver disease in humans and mice, while knockdown of JAK1 and JAK2 inhibited activation, proliferation, and migration of HSCs." (PMID 35382859, 2022). "Based on previous research, JAK1/STAT3 signaling inhibition can relieve the inflammation and ameliorate liver disease." (PMID 37630721, 2023).
metabolic syndrome (3 papers, 2017 to 2025). A cluster of metabolic risk factors for CARDIOVASCULAR DISEASES and TYPE 2 DIABETES MELLITUS. "Similar to IFNG, the expressions of JAK1 and STAT3 were statistically lower in subjects with dyslipidemia (G1, G2, and G3), and significant negative correlations were found between these genes and lipid parameters." (PMID 28316372, 2017). "Patients with dyslipidemia demonstrated statistically higher expression of the IL10 and IFNA genes, while IFNG, IP10, IRF1, JAK1, and STAT3 were lower in comparison with nondyslipidemic patients." (PMID 28316372, 2017).
metastatic melanoma (3 papers, 2015 to 2023). A melanoma that has spread from its primary site to another anatomic site. "Mutations in Janus kinase 1/2 (JAK1/2) and beta-2-microglobulin (B2M) were found in both primary and acquired resistance to anti-PD-1 antibody (pembrolizumab) or anti-CTLA-4 (ipilimumab) in metastatic melanoma patients." (PMID 34827646, 2021).
mycosis fungoides (3 papers, 2024 to 2026). Classical mycosis fungoides is the most common type of mycosis fungoides (MF), a form of cutaneous T-cell lymphoma, and is characterized by slow progression from patches to more infiltrated plaques and eventually to tumors. "A case of rapid worsening of a psoriasiform dermatitis later revealed to be mycosis fungoides has also been reported with use of ruxolitinib, a JAK1/2 inhibitor." (PMID 39507477, 2024).
nonalcoholic fatty liver disease (3 papers, 2021 to 2024). "BP attenuates the severity of colorectal inflammation and liver injuries caused by exposure to dextran sulfate sodium and mitigates nonalcoholic fatty liver disease via JAK1/STAT3/BAX signaling." (PMID 33971886, 2021). "In nonalcoholic fatty liver disease, OPN promoted macrophage M1 polarization by activation of the JAK1/STAT1/HMGB1 signaling pathway." (PMID 38250077, 2023).
Opportunistic infection (3 papers, 2019 to 2024). An infection that is caused by a pathogen that would generally not be able to cause an infection in a host with a normal immune system. "The suppression of T-cell proliferation by ruxolitinib, likely through inhibition of JAK1 signaling by IL-2, may be associated with its increased rate of opportunistic infections in vivo." (PMID 31560729, 2019).
osteoarthritis (3 papers, 2019 to 2023). A noninflammatory degenerative joint disease occurring chiefly in older persons, characterized by degeneration of the articular cartilage, hypertrophy of bone at the margins and changes in the synovial membrane. "Further biological functions of JAK1 and miR-130a-3p in osteoarthritis were illustrated." (PMID 36918905, 2023). "Carboxymethyl chitosan could attenuate inducible nitric oxide synthase and protect against osteoarthritis through the IL-10/JAK1/STAT3 pathway." (PMID 31182999, 2019).
osteoporosis (3 papers, 2017 to 2025). A condition of reduced bone mass, with decreased cortical thickness and a decrease in the number and size of the trabeculae of cancellous bone (but normal chemical composition), resulting in increased fracture incidence. "Molecular docking technology further reveals that the two drugs can produce pathological effects by binding to osteoporosis-related genes such as ADORA1 and JAK1." (PMID 40687725, 2025). "Our findings also offer an innovative aim for therapy of senile osteoporosis and evidence to prompt additional investigation of the interaction between RPN2 and the JAK1/STAT3 pathway in hBMSC osteogenic differentiation." (PMID 31743606, 2020).
prostate adenocarcinoma (3 papers, 2007 to 2020). "An absence of response to IFN in lung and prostate adenocarcinoma cell lines has been attributed to lack of Jak-1 gene expression." (PMID 17319941, 2007).